HEXB (hexosaminidase subunit beta)
Diseases named in the same sentence as HEXB in open-access papers (continued):
Sharing a sentence is not in itself a finding about the gene and the disease.
Tay-Sachs disease (21 papers, 2016 to 2025). GM2 gangliosidosis, variant B or Tay-Sachs disease is marked by accumulation of G2 gangliosides due to hexosaminidase A deficiency. "Bypassing the HexA/GM2AP-dependent degradation of GM2 to GM3 with Neu3 to yield GA2 facilitates the complete degradation of GA2 by HexB in the Tay-Sachs disease mouse model (Hexa-deficiency)." (PMID 37972730, 2023). "Mutations in either the HEXA or HEXB gene cause the GM2 gangliosidoses Tay-Sachs disease (TSD) or Sandhoff disease (SD), respectively." (PMID 39752451, 2025). "Gene therapy for infantile Tay-Sachs disease has involved the use of 2 monocistronic AAV vectors separately encoding the HEXA and HEXB genes." (PMID 40526437, 2025). "Biallelic mutations in HEXA, which encodes the α subunit, cause Tay-Sachs disease (TSD); biallelic mutations in HEXB, which encodes the β subunit, cause Sandhoff disease (SD)." (PMID 39276676, 2024). "Mutations in the genes encoding the α- (HEXA) and β-subunits (HEXB), or GM2A (GM2A) lead to Tay-Sachs Disease (TSD; OMIM #272800), Sandhoff Disease (SD; OMIM #268800) and AB-Variant GM2 gangliosidosis (ABGM2; OMIM #272750), respectively." (PMID 38098938, 2023). "Three clinically similar subtypes of GM2 exist: Tay-Sachs disease (TSD), Sandhoff disease (SD), and GM2 activator deficiency, which result from mutation of HEXA, HEXB, and GM2A genes, respectively." (PMID 34456684, 2021).
GM2 gangliosidosis (16 papers, 2012 to 2026). A group of recessively inherited diseases characterized by the intralysosomal accumulation of G(M2) GANGLIOSIDE in the neuronal cells. "Thus HEXB-deficient mice can be useful for the initial evaluation of potential GM2-gangliosidosis treatment." (PMID 30524313, 2018). "GM2-gangliosidosis can be caused by mutations in three genes: HEXA (15th chromosome), HEXB (5th chromosome), and GM2A (5th chromosome)." (PMID 30524313, 2018). "For these reasons, the HexB−/− knockout mouse is widely accepted as the appropriate animal model in the study of GM2 gangliosidosis." (PMID 22863301, 2012). "This condition is caused by loss of function variations in beta-hexosaminidase subunit beta protein, and the phenotype of GM2 gangliosidosis is indistinguishable from that of Tay–Sachs disease." (PMID 36358909, 2022). "Therefore, in the mouse HexB disruption results in GM2 gangliosidosis, whereas in the human either HEXA or HEXB mutations can cause GM2 storage." (PMID 22863301, 2012). "Hence, deficiency of any of these proteins that are encoded by the HEXA, HEXB, and GM2A genes, respectively, causes excessive intra lysosomal accumulation of GM2 gangliosides and related glycolipids, especially in neuronal cells resulting in GM2 gangliosidosis." (PMID 32883051, 2020).
lysosomal storage disorder (14 papers, 2011 to 2025). "The upregulation of LAMP1, lysosomal enzymes (HEXB and NAGLU) as well as autophagy has been found in multiple lysosome storage diseases (LSDs)." (PMID 35215314, 2022).
GM1 gangliosidosis (4 papers, 2016 to 2020). A rare lysosomal storage disorder characterized biochemically by deficient beta-galactosidase activity and clinically by a wide range of variable neurovisceral, ophthalmological and dysmorphic features. "Furthermore, we detected that three other patients, an infant with GM1 gangliosidosis, an infant with MPS 3A, and an adult with type 2 elliptocytosis, were also carriers of confirmed pathogenic mutations in the SMPD1, SLC17A5, and HEXB genes, respectively." (PMID 32071839, 2020).
Ataxia (3 papers, 2022 to 2024). Ataxia refers to impaired coordination of voluntary muscle movement. "AR2 (HEXB) and AR278 (ATP1A3), with one patient each, presented ataxia and dystonia." (PMID 35326432, 2022).
Cognitive impairment (3 papers, 2022 to 2025). Abnormal cognition is characterized by deficits in thinking, reasoning, or remembering. "Endo-lysosomal proteins (e.g., HEXB, TPP1, SIAE) increased early in abundance alongside neurodegeneration-related proteins, and were followed by increases in metabolic proteins such as ALDOA, MDH1, and GOT1 at the mild cognitive impairment (MCI) stage." (PMID 40329321, 2025).
glioblastoma (3 papers, 2021 to 2024). The most malignant astrocytic tumor (WHO grade IV). "HEXB may also play a role in pathology, with elevated gene expression of HEXB associated with poor prognosis in human glioblastoma." (PMID 38425429, 2024). "And the higher expression of HEXB is associated with poor prognosis in glioblastoma patients." (PMID 37168863, 2023).
glioma (3 papers, 2021 to 2024). A benign or malignant brain and spinal cord tumor that arises from glial cells (astrocytes, oligodendrocytes, ependymal cells). "Interestingly, CGGA database showed that the expression level of HEXA and HEXB was higher in the highest-grade glioma (WHO IV), than that in low-grade gliomas." (PMID 34422641, 2021). "Meanwhile, other grade gliomas patients with higher expression of HEXA and HEXB mRNA expression were also predicted the lower survival probability." (PMID 34422641, 2021). "Interestingly, all WHO grades of gliomas patients with higher HEXA and HEXB expression were predicted a poor prognosis." (PMID 34422641, 2021).
Alzheimer disease (2 papers, 2022 to 2025). A progressive, neurodegenerative disease characterized by loss of function and death of nerve cells in several areas of the brain leading to loss of cognitive function such as memory and language. "HEXB was mainly enriched in the lysosome, chemokine signaling pathway, spliceosome, oxidative phosphorylation, Alzheimer’s disease, hematopoietic cell lineage, regulation of actin cytoskeleton, and Parkinson’s disease pathways." (PMID 40534738, 2025).
Gaucher disease (2 papers, 2023). Gaucher disease (GD) is a lysosomal storage disorder encompassing three main forms (types 1, 2 and 3), a fetal form and a variant with cardiac involvement (Gaucher disease - ophthalmoplegia - cardiovascular calcification or Gaucher-like disease). "The inflammation markers chitotriosidase (CHIT1) and β-hexosaminidase (heterodimer or homodimer of HEXA and/or HEXB) are markedly increased in the serum of Gaucher's disease patients and used as biomarkers to monitor disease activity." (PMID 36951087, 2023).
lysosomal lipid storage disorder (2 papers, 2018 to 2019). An inherited metabolic disorder in which harmful amounts of lipids accumulate in cells and tissues. "GM2 gangliosides are a group of lysosomal lipid storage disorders that resulted from disease-causing mutations in three autosomal recessive genes, including hexosaminidase A (HEXA), hexosaminidase subunit beta (HEXB) and GM2 ganglioside activator (GM2A)." (PMID 31428437, 2018).
preeclampsia (2 papers, 2013 to 2026). Preeclampsia is a hypertensive disorder of pregnancy that is characterized by new-onset hypertension with proteinuria presenting after 20 weeks of gestation, and depending on mild or severe forms may initially present with severe headache, visual disturbances, and hyperreflexia. "Other genes as SPAG4, HEXB, TPI1 and QSOX1 are basically unknown in preeclampsia (and even during normal pregnancy)." (PMID 24219996, 2013).
schizophrenia (2 papers, 2020 to 2021). A major psychotic disorder characterized by abnormalities in the perception or expression of reality. "HEXB mRNA was increased in bipolar disorder compared to schizophrenia (14%, p = 0.025) and P2RY13 mRNA was reduced in bipolar disorder compared to controls (37%, p = 0.003)." (PMID 34911938, 2021). "When comparing the inflammatory subgroups, HEXB mRNA again showed a trend toward an overall change (F = 2.74, df = 50,2, p = 0.074); however, this was due to a small increase (17.6%) in HEXB gene expression in the low inflammatory/schizophrenia subgroup compared to the control group (p = 0.025)." (PMID 33133060, 2020). "Based on a dichotomous variable indicating history of antidepressant use, schizophrenia cases that had been prescribed antidepressants had lower expression of FCGR3A and HEXB mRNAs." (PMID 34911938, 2021). "HEXB gene expression in the high inflammatory/schizophrenia subgroup was not significantly different from the low inflammatory/schizophrenia subgroup or the control group (both p > 0.05)." (PMID 33133060, 2020). "However, HEXB mRNA, which is highly and uniquely expressed in all microglia (including resting), and not expressed by peripheral macrophages, was not significantly changed in those with schizophrenia in our study." (PMID 33133060, 2020).
bipolar disorder (1 paper, 2021). A disorder of the brain that causes unusual shifts in mood, energy, activity levels and the ability to carry out day-to-day tasks. "In bipolar disorder cases that had been prescribed antidepressants, there was reduced expression of FCGR3A, IBA1 and P2RY12 mRNAs and higher expression of HEXB mRNA." (PMID 34911938, 2021).
epilepsy (1 paper, 2022). A brain disorder characterized by episodes of abnormally increased neuronal discharge resulting in transient episodes of sensory or motor neurological dysfunction, or psychic dysfunction. "Given the functional contributions of GM2A, HEXA, and HEXB to lysosomal degradation of GM2 gangliosides, we next investigated lysosomal localization of GM2 gangliosides in GSCs in comparison with nonmalignant neural cultures from epilepsy patient surgical specimens." (PMID 35133980, 2022).
Granuloma (1 paper, 2022). A compact, organized collection of mature mononuclear phagocytes, which may be but is not necessarily accompanied by accessory features such as necrosis. "When compared to granuloma periphery or mucosa, CD68+ cells in the granulomata demonstrated increased gene expression in lysosome or macrophage-related genes such as CTSD, CD68, HEXB, ATP6V0A1, CTSK, LIPA, CD63." (PMID 36302964, 2022).
ischemic stroke (1 paper, 2016). A stroke disorder caused by obstruction of blood flow to the brain, due to thrombotic (local blood clot formation) or embolic (due to a blood clot or other material traveling from another site) event. "The only functional assay indicated that this miRNA targets the HEXB gene and may regulate lysosomal-associated proteins following ischemic stroke." (PMID 27695061, 2016).
keloid (1 paper, 2023). An irregularly shaped, elevated mark on the skin caused by deposits of excessive amounts of collagen during wound healing. "We explored the potential role of GSL metabolism pathway in keloid, classfied keloids based on GSLMRGs expression patterns, provided a set of gene markers including GLTP, GALC, ARSA, HEXB, SUMF2, and GBA2, and constructed a diagnostic model for keloid." (PMID 37168863, 2023). "A strong correlation between IL-7 and GLTP, GALC, ARSA, HEXB, and SUMF2 was found, suggesting that IL-7-based inflammatory factors may involve in keloid growth and development through associating with the GSL metabolism pathway." (PMID 37168863, 2023). "In this study, the differential GSLMRGs of keloid and the top ten genes with the highest importance from machine learning algorithms Random Forest and SVM-RFE were intersected, and six candidate GSLMRGs were identified: ARSA, GBA2, SUMF2, GLTP, GALC, and HEXB." (PMID 37168863, 2023).
neuroblastoma (1 paper, 2025). Neuroblastoma (NB) is the most common solid, extracranial childhood tumor. "Transfection with HEXA/HEXB cDNA resulted in higher enzyme activity, especially in NIH-3T3 fibroblasts, SHSY5Y neuroblastoma, and TSD fibroblasts, compared to transfection with HEXA cDNA." (PMID 40430919, 2025).
ovarian carcinoma (1 paper, 2014). A malignant neoplasm originating from the surface ovarian epithelium. "One branch clustered eight genes (NAGA, B4GALT6, HEXA, GLB1, GBA, GLA, UGCG, HEXB) with generally comparable expression levels among the cell lines, except for the UGCG gene which was expressed at considerably higher levels in both HOSE cell lines compared with the ovarian cancer cell lines." (PMID 25294702, 2014).
type 1 diabetes (1 paper, 2020). "Interestingly, all enzymes involved in keratan sulfate degradation (ie., GALNS, GLB1, GNS, HEXA, and HEXB) were elevated in urines from youths with type 1 diabetes, compared to non-diabetic youths." (PMID 32453760, 2020).
tumor (6 papers, 2012 to 2025). "Supporting tumor secretion of HEXB, reinterrogation of quantitative proteomics data of a large CRC plasma cohort, revealed elevated HEXB protein levels in plasma from CRC patients relative to healthy controls." (PMID 39947398, 2025). "Taken together, our collection of -omics data suggests that tumor-infiltrating monocytes contributes to the enhanced HEXB gene expression in CRC tumors, which results in elevated copy numbers of soluble HEXB protein molecules that are predominantly secreted into circulation." (PMID 39947398, 2025). "Surprisingly, a HEXB-focused reinterrogation of quantitative proteomics data of paired tissue samples from 96 CRC patients available from Clinical Proteomic Tumor Analysis Consortium showed only mild (insignificant) increase of HEXB protein levels in TUM compared to NAT." (PMID 39947398, 2025). "Similarly to GM2A depletion, loss of either HEXA or HEXB decreased GSC growth and abolished tumor sphere formation." (PMID 35133980, 2022). "Other enzymes in the same signature belonging to the lysosomal pathway of ganglioside catabolism, such as Hexosaminidase Subunit Beta (HEXB) and Neuraminidase 1 (NEU1), were also overexpressed in tumor samples of both LIHC and LIRI-JP." (PMID 38927057, 2024).
cancer (5 papers, 2017 to 2025). A tumor composed of atypical neoplastic, often pleomorphic cells that invade other tissues. "Aberrations in the expression of paucimannosidic proteins and HEXB in CRC are also interesting in a cancer marker context." (PMID 39947398, 2025). "The function of membrane-bound cytochrome b5 reductase 3 (CYB5R3) and hexosaminidase subunit beta (HEXB) on cancers is still unclear." (PMID 34557495, 2021). "The function of CYP2C9, DPH2, EIF2B4, and HEXB on cancer remains unclear, and their biological effects and clinical significance wait for further research in HCC." (PMID 39041652, 2024). "β-Hexosaminidase (HEXB), an enzyme found predominantly in lysosomes, is not implicated in cancer to our knowledge." (PMID 29207636, 2017). "While still largely unexplored in cancer cells, the formation of paucimannosidic N-glycans through an only recently discovered truncation pathway involves most critically the HEXA and HEXB among other glycoside hydrolases to form M3(F) and further truncated structures." (PMID 39947398, 2025). "No influence of two genes (CYB5R3 and HEXB) in cancers has been reported, but our study found that upregulation of CYB5R3 and HEXB was significantly linked to the poor prognosis of HCC patients." (PMID 34557495, 2021). "Moreover, HEXA, HEXB, MAN2A1, and MAN2B1 were overexpressed in cancer relative to healthy stomachs from individuals without gastric pathologies." (PMID 41041068, 2025).
infection (4 papers, 2018 to 2025). The state of being infected such as from the introduction of a foreign agent such as serum, vaccine, antigenic substance or organism. "Substrates for HexB are acidic GSLs, which are implicated in specific infection." (PMID 38029258, 2023). "HEXB is upregulated in the early stages of infection and downregulated in the later stages, which is consistent with our qRT-PCR results." (PMID 40003829, 2025). "Proinflammatory cytokine TNF-α and lysosomal enzyme HEXB effectively contribute to bactericidal activity at this time point of infection." (PMID 35631117, 2022). "At 96 h post-infection, CYP307A1, NPC2, and HEXB are significantly upregulated compared to 72 h, indicating a shift in immune strategy." (PMID 40003829, 2025).
neurodegenerative disease (3 papers, 2025). A disorder of the central nervous system characterized by gradual and progressive loss of neural tissue and neurologic function. "This study revealed that the five biomarkers, GLB1, ARSB, ASAH1, HEXB, and PSAP are all enriched in the lysosomal, chemokine, oxidative phosphorylation, and neurodegenerative disease pathways." (PMID 40534738, 2025).
metabolic disease (2 papers, 2016 to 2019). A congenital disorder (due to inherited enzyme abnormality) or acquired (due to failure of a metabolically important organ) disorder resulting from an abnormal metabolic process. "Interestingly both protein products of MBOAT7 and HEXB genes are involved in metabolic disorders of lipid biosynthesis and remodeling within the brain, and this group of disorders are an important and often overlooked consideration in the differential diagnosis of neurodevelopmental disorders." (PMID 31852446, 2019).
HEXB also shares sentences with these, for which no sentence is quoted: Gliosis (2 papers); Krabbe disease (2); melanoma (2); neurologic disease (2); neuropathy (2); sphingolipidoses (2); astrocytoma (1); Autoimmunity (1); cerebellar ataxia (1); Cirrhosis (1); diabetes (1); Dystonia (1); Fabry disease (1); gangliosidosis (1); gastric cancer (1); genetic diseases (1); hairy cell leukemia (1); infectious encephalitis (1); Lipid storage disease (1); liver cancer (1); metachromatic leukodystrophy (1); movement disorder (1); mucopolysaccharidosis VI (1); neurodevelopmental disorder (1); neuronal ceroid lipofuscinosis (1); Niemann-Pick disease (1); Obesity (1); obstructive hydrocephalus (1); osteoarthritis (1); osteoporosis (1).
A further 8 diseases each share a sentence with HEXB in 1 paper.